TNF (tumor necrosis factor)
Diseases named in the same sentence as TNF in open-access papers (continued):
Sharing a sentence is not in itself a finding about the gene and the disease.
viral infection (continued). "Furthermore, inflammatory responses induced by various microbial and viral infections led to the production of pro-inflammatory cytokines such as TNF-α, IL-6, and IL-1β in macrophages via upregulation of the PI3K/AKT and MAPK pathways." (PMID 32867320, 2020). "In contrast to non-cytopathic virus infection, our study suggests that the CNS innate response mechanism has a relatively higher-level synergy between MDA5, IRF1, CCL5, TNF-α, and IFN-γ to compensate for the IFN-I signaling loss to deal with a cytopathic virus infection." (PMID 32575459, 2020). "The pathway enrichment analysis of the FDEGs then showed that the TNF signaling pathway, Toll-like receptor signaling pathway, and some viral-infection-related pathways (influenza A, measles, and herpes simplex) were the main pathways in multi-organ damage of LPS-mediated endotoxemic mice." (PMID 33330617, 2020). "In particular we observed that knockout of Pellino-1 in the murine lung resulted in increased production of proinflammatory cytokines IL-6 and TNFα upon viral infection, accompanied by enhanced recruitment of immune cells to the airways, without any change in viral replication." (PMID 32984077, 2020). "The leading contribution of MCs in response to viral infection might be in the context of the producing panel of mediators (amines, tryptase, chymase) and cytokines/chemokines (TNF-α, IL-4, IL-5, IL-6, IL-13, and IL-17)." (PMID 32185237, 2020). "Additionally, viral infection can affect hematopoiesis through the action of mediators such as type I IFNs, TNFα, and other cytokines generated during the infection." (PMID 32373117, 2020). "Our current study suggests that TNF-α is not the sole factor driving weight loss after viral infection." (PMID 32071269, 2020). "In intracellular infections, iNKT cells are characterized by release of cytokines such as IFN-γ, TNF-α, IL-4, IL-5, IL-13, IL-17, chemokines, and rapid effector functions as in Salmonella, Ehrlichia, M. tuberculosis, Trypanosoma cruzi, and many viral infections." (PMID 31111075, 2019). "NK cells work to control viral infections by secreting IFNγ and TNFα." (PMID 31396204, 2019). "Of note, through careful infectious screening and serological monitoring, anti-TNF-α therapy could be safely used even in hemophiliacs presenting viral infections, which are usually considered a major contraindication for this kind of treatment." (PMID 31261789, 2019). "During viral infections, the increased TNF presence would trigger TNFR1 and TNFR2." (PMID 31541082, 2019). "Similarly, tumor necrosis factor-α levels were increased 4.89-fold following viral infection, whereas treatment with Celecoxib brought TNFα levels back to basal levels." (PMID 31842327, 2019). "During viral infection, concomitant blockade of both TNF and a reduced set of chemokines by a single secreted protein was found to completely abrogate local inflammation in the mousepox intradermal infection model, effectively ablating the host response to produce a lethal infection." (PMID 31877657, 2019). "Further, the viral particle of baculovirus is able to evoke robust innate immune responses by regulating cytokines such as interleukin 6 (IL-6) and tumor necrosis factor alpha (TNF-α), which may take place in blocking the viral infection." (PMID 29954081, 2018). "It has been speculated that elevated IFNs, TNF-α, and IL-6 during viral infection correlated with the severity and outcome of viral diseases." (PMID 30016363, 2018). "Moreover, this unique model of virus infection in a natural host, together with the construction of mutant viruses, allowed us to dissect the relative contribution of TNF and chemokine activities in vivo." (PMID 29724993, 2018). "Whether the changes in the levels of TNFα and TNFRs at 4–5 dpi are consequent to seizures or viral infection itself, or the seizures are precipitated after an increase in TNFα-TNFR1 signaling or decrease in TNFα-TNFR2 signaling is not clearly understood." (PMID 28497109, 2017).
viral infection (continued). "Moreover, nuclear localization of caspase-1 and inflammasome components, and also formation of active nuclear inflammasomes in response to viral infections and TNF-α was previously demonstrated." (PMID 28153032, 2017). "For example, tumor necrosis factor (TNF), toxic materials, viral infections, and radiations initiate apoptosis, while aberrant expression of growth factors may result in deregulation of apoptosis." (PMID 29163803, 2017). "Our data demonstrate that during virus infection cells with a high content of FL-gSeV are susceptible to TNFα but not type-I IFN mediated apoptosis." (PMID 28986577, 2017). "Notably, co-infections led to a significant increase in the levels of TNF-α and IL-6, cytokines that are widely considered to play a crucial role in the early pathogenesis of both viral diseases." (PMID 28644900, 2017). "They had a prominent systemic immune response involving IL-6, TNF-α, and MCP-1 which may be due to the activation of macrophages that was caused by the viral infection." (PMID 28352642, 2017). "In viral infection, cytokine expression is also elevated through a TNF-α/NF-κB-related pathway." (PMID 28950910, 2017). "We have previously published that CS exposure (without viral infection) was associated with higher protein levels of TNF-α, MIP-2, GM-CSF and IFN-γ in BALF than in no-smoke mice, especially at d1010." (PMID 26877172, 2016). "IL-6 is extremely inducible in response to IL-1, TNFα, viral infection and angiotensin II peptide." (PMID 27884156, 2016). "TNF-α plays an important role in host defense against viral infection." (PMID 27329558, 2016). "Some recent reports have shown that anti-TNFα therapies could be utilized to treat certain viral infections." (PMID 27351838, 2016). "Although the administration of anti-TNFα therapies normally aggravates viral infections, there are a few reports suggesting that TNFα inhibition could be beneficial for the treatment of certain viral infections." (PMID 27351838, 2016). "It is likely that many acute viral infections induce transient alterations on the hematopoietic process, through the action of mediators such as type I IFNs, TNF, and lymphotoxin (LT), as has been described in mice models of lymphocytic choriomeningitis virus (LCMV) and Influenza infections." (PMID 27695457, 2016). "Because it has been suggested that cells simultaneously producing IFN-γ, IL-2, and TNF-α may provide optimal effector function and protection against viral infections, we defined the proportions of bifunctional cells in our immunized animals." (PMID 27183611, 2016). "In the present study, TNF-α was used as a stimulus to elucidate whether G6PD knockdown affects the inflammatory response against viral infection." (PMID 27097228, 2016). "This may be consistent with studies suggesting that antigen-activated CD8+ T lymphocytes can eliminate or control viral infection by secretion of IFNγ and TNFα [38, –40]." (PMID 27709126, 2016). "Viral infection may promote tumoral infiltration by inducing the production of tumor necrosis factor-alpha (TNF-α), IL-6, and IL-1a in keratinocytes." (PMID 27540476, 2016). "The results indicate that virus infection might enhance TNF-α responses to minor bacterial infection." (PMID 26284064, 2015). "The capacity of CD8+ T cells to produce multiple effector cytokines such as IFN-β and TNF-α has also emerged as a positive correlate of effective CTL immunity after virus infection, suggesting that CD8+ T cells contribute to the primary mechanism of virus clearance." (PMID 26437715, 2015). "Up on viral infection macrophages have been shown to produce cytokines like IL-15, TNF-α and IL-12." (PMID 26085921, 2015). "Upon viral infection, both in vitro and clinical studies have shown TNF expression in neurons." (PMID 26112704, 2015).
viral infection (continued). "In this study, the expression levels of the majority of genes involved in the TNF signaling pathway, including those encoding TNF, IL-6, CCL20, caspase 10, caspase 3, NF-κB, and TGF-β-activated kinase 1 (TAK1), were significantly downregulated after viral infection." (PMID 25423176, 2014). "A variety of stimuli can activate the NF-κB response, such as cytokine stimuli (Tumor Necrosis Factor –α [TNF-α], Interleukin-1 [IL-1]), UV stress, DNA damage, lipopolysaccharide and virus infection, which result in p65 nuclear translocation and transcription regulation." (PMID 24586253, 2014). "Inflammatory processes induced by viral infection are considered an important pathogenic mechanism in acute myocarditis or DCM, and tumor necrosis factor (TNF)-α and interleukin (IL)-1β may be the dominant inflammatory cytokines expressed in viral myocarditis." (PMID 25462010, 2014). "NF-κB signaling, which regulates a number of inflammatory genes, including iNOS, COX-2, TNF-α, IL-1β, and IL-6, can be stimulated by pathological stimuli, such as viral infection, UV radiation, and free radicals, and its dysregulation is involved in the pathogenesis of many inflammatory disorders." (PMID 24475143, 2014). "Normally, virus infection may enhance IL-1α, IL-1β and TNF-α expression that consequently inhibits virus replication." (PMID 23527143, 2013). "However, as the complete knockout of TNF or its receptors has effects on multiple cell types as well as on lymphoid architecture, it has been difficult to assess the role of TNF directly on T cells during viral infection." (PMID 23874808, 2013). "Thus, elevation of IL-4Rα expression on CD8+ T cells during virus infection strongly correlated with the reduction of anti-viral IFN-γ+ TNF-α+ CD8+ T cell responses." (PMID 23383283, 2013). "It was believed that all anti-TNF-α agents would increase the development of serious fungal, bacterial, or viral infections that could be attributed to malignancy by suppression of the immune response." (PMID 24578833, 2013). "Additionally, we reveal transient changes in nitric oxide (NO) levels to be a notable feature of response to viral infection and LN vascular remodeling and provide evidence that mast cells are the critical source of TNFα required to drive arteriole remodeling." (PMID 23573281, 2013). "The induction of pro-inflammatory cytokines such as COX-2, TNF, IFNs, IL27 and CXCL10 is essential for the host immune response during virus infection, but inappropriately sustained induction causes cytokine-storms, which are associated with a wide variety of infectious diseases." (PMID 24138989, 2013). "Other viral infections frequently seen by dermatologists that may be exacerbated by anti-TNF therapy include herpes zoster, primary varicella, and molluscum contagiosum." (PMID 24368947, 2013). "The results showed that local inhibition of TNF-α could significantly reduce the high mortality in mice induced by lethal influenza infection, which indicated that TNF-α in lung tissue might play a pathologic role in severe virus infection." (PMID 24373231, 2013). "The early host response to viral infections involves transient activation of pattern recognition receptors leading to an induction of inflammatory cytokines such as interleukin-1β (IL-1β) and tumor necrosis factor α (TNFα)." (PMID 22319449, 2012). "During the first 1–4 day after virus infection, virus are replicated in cardiac myocytes and trigger innate immune signaling, which contribute to the increasing expression of pro-inflammatory cytokines including TNF-α, IL-6, IL-1β and chemokines." (PMID 23029542, 2012). "Interestingly, response to TLR3 ligands and to viral infection is upregulated in inflammatory conditions (including exposure to tumor necrosis factor (TNF)-α) or during inflammatory disorders." (PMID 22879901, 2012).
viral infection (continued). "We speculate that miR-125b may be one of the regulators of the TNF-α response during viral infection, and that regulation of miR-125b may require an intact IFN response." (PMID 20169186, 2010). "Bacterial or viral infection may play a role in triggering the development of RA and TNFα and iNOS are key players in enhanced antimicrobial activity of activated macrophages." (PMID 19710928, 2009). "Smoke exposure (without viral infection) was generally associated with higher protein levels of cytokines (e.g. TNF-α, MIP-2, GM-CSF, IFN-γ) in BALF than in no-smoke mice, especially at d10." (PMID 18627612, 2008). "In AdLacZ infected HUVECs, IL-6 and IL-8 mRNA levels exhibited higher and lower increases, respectively, upon TNF-α stimulation compared to uninfected HUVECs, which may be a result of viral infection per se." (PMID 16803639, 2006). "IFN-α or TNF-α pre-treatment prior to virus infection may restore cell machinery to induce the IFN production." (PMID 16945160, 2006). "For example, IFNs, which are used to treat viral infections, can activate immune cells and induce the production of anti-inflammatory cytokines, such as IL-10, while inhibiting the production of pro-inflammatory cytokines, such as tumor necrosis factor (TNF)-α and IL-6." (PMID 40746413, 2025). "Humans expressing loss-of-function (LoF) TBK1 mutations do not suffer from excessive viral infections but do suffer from excessive cell death–driven inflammation in a steady state largely mediated via uncontrolled TNF (tumor necrosis factor)–RIPK1–driven cell death." (PMID 40053580, 2025). "When the immune system is combating a viral infection, NK cells may exert a dual role, for they not only produce TNF-α and IFN-γ to modulate the immune response but also directly kill virus-infected cells through cytotoxic mediators such as perforin and granzymes." (PMID 40680069, 2025). "Moreover, increased bacterial adhesion may be mediated not only by virus infection but also by pro-inflammatory cytokines such as IL-6, IL-1α, and TNF-α, which upregulate receptors like ICAM-1, PAFr, and CEACAM1." (PMID 40520162, 2025). "Chronic inflammation, triggered by bacterial or viral infections or autoimmune processes, generates an environment rich in pro-inflammatory cytokines, such as interleukin-1 beta (IL-1β), tumor necrosis factor-alpha (TNF-α), and interleukin-6 (IL-6), which directly impact cerebral endothelial cells." (PMID 40141084, 2025). "Importantly, virus infection with both strains also resulted in an enhancement of TNFα production at 24- and 48-hours post-infection by HI-Ro-primed macrophages, demonstrating the capacity of infected cells to overcome the virus-induced innate immune suppression characteristic of ASFV." (PMID 40529370, 2025). "Thus, the high level of TNFα detected in the amniotic fluid (200 pg/mL) may represent an inflammatory response state induced by the virus infection." (PMID 39998269, 2025). "Given the importance of IL-6, TNF-α, IL-12p40, and IL-27 in aiding the immune system during viral infections such as influenza, vaccinia virus, HIV, and herpes simplex and supporting viral immunity, a fermentate that can enhance these cytokines could be beneficial." (PMID 38674902, 2024). "Additionally, DE cis-lncRNA pathways included type I diabetes mellitus, epstein−Barr virus infection, graft−versus−host disease, and antigen processing and presentation, while DE trans-lncRNA pathways involved dopaminergic synapse, apoptosis, TNF signaling pathway and chemokine signaling pathway." (PMID 39170713, 2024). "Therefore, we wanted to examine whether different cellular stress conditions, including FCS starvation, IFNγ treatment, TNF treatment, viral infection (LCMV) and heat-shock, lead to enhanced DRiP formation in our set-up." (PMID 39247192, 2024).
viral infection (continued). "Furthermore, SARS-CoV-2 miRNAs can also be transported to host cells during viral infection and bind to host miRNAs and genes to target host immune-related genes, which directly/indirectly coordinate immune pathways, such as tumor necrosis factor (TNF) signaling and chemokine signaling." (PMID 36593971, 2023). "Evidently, IL-4 produced by Th2 cells and natural killer T (NKT) cells is critical for antiviral CD8+ T-cell (IFN-γ- and TNF-α–secreting cell) functions and antibody development during early viral infections, all of which are essential for inhibiting the establishment of persistent virus infections." (PMID 37235332, 2023). "Finally, we found a positive regulation of genes related to immune response to virus infections (Type I Interferons, inflammatory cytokines (IL-6, TNF and NF-κB), NLRP3 inflammasome, anti-inflammatory cytokines (IL-10), and cell death pathways (pyroptosis and apoptosis)) in RA individuals." (PMID 37628893, 2023). "The treatment with piceatannol significantly increased the serum levels of IFN-γ and TNF-α in the infected mice, suggesting that piceatannol could enhance the inflammatory response and inhibit virus replication at the early stage of virus infection by increasing the levels of TNF-α and IFN-γ." (PMID 37508153, 2023). "However, its application remains still controversial, for the fact that the application of TNF-α inhibitors may increase the risk of bacteria and fungi co-infections and that the side effects of using TNF inhibitors in viral infections is unclear." (PMID 37476615, 2023). "In addition, kidney cells derived from E. fuscus limit expression of the pro-inflammatory cytokine, tumor necrosis factor alpha (TNFα) in response to surrogate virus infection [poly(I:C) stimulation] because of the activity of a TNFα promoter repressor protein, c-Rel." (PMID 35875684, 2022). "Therefore, TNF+Poly(I:C)-dependent expression of antigen presentation pathway may provide a conceptual basis for enhanced antigen presentation involving signaling from DAMPs or viral infections in the context of TNF-driven inflammation during active IBD." (PMID 35655783, 2022). "Furthermore, this finding may contribute to a novel understanding of the endogenous TNF-α usage in viral infection." (PMID 35268699, 2022). "Reduction of TNF-α by treatment with TNF-α blockade may increase the risk of developing a viral infection such as HPV or not being able to resolve an infection when it occurs." (PMID 35449072, 2022). "Moreover, virus infection enhanced the expressions of TNF-α, IL-1β, IL-6, IL-10, IFN-α, and IFN-β." (PMID 33827620, 2021). "Hence, GAPDH upregulation by IFN-I may contribute to apoptosis induction and TNFα repression in R. aegyptiacus, which could represent novel mechanisms for the prevention of excessive inflammation during viral infections." (PMID 34737406, 2021). "This magnification of TH1 associated cytokines and TNF-α is significant, as co-production of IFN-γ, IL-2, and TNF-α on polyfunctional antigen-specific T-cells has been shown to be the strongest criteria for predicting vaccine-elicited T-cell mediated protection against viral infection." (PMID 34603303, 2021). "TNF is a potent pro-inflammatory cytokine with a broad range of biological effects, ranging from the activation of inflammatory gene programs to cell differentiation or apoptosis induction while also playing an essential role in the host control of many viral infections." (PMID 34451529, 2021). "Many different extra- and intra-cellular signals including virus infection and TNFα can lead to activation of the canonical NF-κB pathway, and although the upstream receptors and receptor-associated proteins may be unique to each signal, all pathways converge on the IKK complex." (PMID 33807175, 2021).